PIGL (phosphatidylinositol glycan anchor biosynthesis class L)
Description:
Catalyzes the second step of glycosylphosphatidylinositol (GPI) biosynthesis, which is the de-N-acetylation of N-acetylglucosaminyl-phosphatidylinositol.
Synonyms: PIG-L; CHIME
Tractability: Antibody: UniProt predicts a signal peptide or a membrane-spanning region.
Gene: Protein-coding gene on chromosome 17 (16,217,191 to 16,351,797, forward strand). Ensembl gene ENSG00000108474.
Subcellular location: Endoplasmic reticulum membrane
Subcellular location (Human Protein Atlas): Cytosol; Nucleoplasm
Pathways (Reactome):
Metabolism of proteins: Synthesis of glycosylphosphatidylinositol (GPI)
Gene Ontology:
Molecular function: N-acetylglucosaminylphosphatidylinositol deacetylase activity
Biological process: GPI anchor biosynthetic process
Cellular component: endoplasmic reticulum membrane; endoplasmic reticulum
Genetic constraint (gnomAD): Loss-of-function variants: 14 observed, 17.67 expected, observed/expected ratio (o/e) 0.79, 90% interval 0.52 to 1.24. The upper end of that interval is the gene's LOEUF score, 1.24, which puts it in group 5 of 6, group 1 being the genes least tolerant of losing a copy. Missense variants: 204 observed, 220.62 expected, observed/expected ratio (o/e) 0.92, 90% interval 0.82 to 1.04. Synonymous variants: 98 observed, 89.55 expected, observed/expected ratio (o/e) 1.09, 90% interval 0.93 to 1.29.
Gene-disease validity (ClinGen):
ClinGen rates the evidence that PIGL causes each of these diseases.
syndromic intellectual disability (autosomal recessive): Definitive. A intellectual disability that is part of a larger syndrome.
Homologues: Orthologues: chimpanzee PIGL (99% identical), macaque PIGL (96% identical), dog PIGL (83% identical), guinea pig PIGL (83% identical), mouse Pigl (79% identical), rat Pigl (77% identical), pig PIGL (69% identical), tropical clawed frog pigl (56% identical), zebrafish pigl (48% identical), Drosophila melanogaster PIG-L (43% identical), Caenorhabditis elegans pigl-1 (36% identical).
Diseases named in the same sentence as PIGL in open-access papers:
PIGL is named in the same sentence as 18 diseases in open-access papers, as found by Europe PMC text mining. Sharing a sentence is not in itself a finding about the gene and the disease. The quoted sentences say what the papers report.
CHIME syndrome (7 papers, 2014 to 2023). CHIME syndrome is a rare ectodermal dysplasia syndrome characterized by ocular colobomas, cardiac defects, ichthyosiform dermatosis, intellectual disability, conductive hearing loss and epilepsy. "Coloboma–congenital heart disease–ichthyosiform dermatitis–mental retardation–ear anomalies (CHIME) syndrome [OMIM:280000] is an AR CDG resulting from mutations in the phosphatidylinositol glycan anchor biosynthesis class L (PIGL) gene on chromosome 17p11.2." (PMID 37239976, 2023). "Mutations in PIGL cause the CHIME syndrome that is characterized by colobomas, heart defects, ichthyosiform dermatosis, mental retardation, and ear anomalies." (PMID 24782851, 2014). "CHIME syndrome (MIM 280000), also known as Zunich Neuro-Ectodermal syndrome was found to be due to mutations in PIGL (MIM 605947)." (PMID 25885527, 2015). "PIGL mutations, causing GPI deficiency, lead to the CHIME syndrome, a collective systemic disorders characterized by colobomas, congenital heart defects, early onset migratory ichthyosiform dermatosis, mental retardation, and ear anomlies." (PMID 25250048, 2014). "To date, PIGL mutations have been reported in seventeen individuals mainly with CHIME syndrome (high ALP but no ichthyosiform dermatosis in four individuals made the presentation more suggestive of HPMRS)." (PMID 32466763, 2020). "Patients with CHIME syndrome (a recessive trait) commonly have a homozygous Leu167Pro mutation, in exon 5 of the PIGL gene; heterozygotes have no disease phenotype." (PMID 25250048, 2014). "Interestingly,individuals presenting two null mutations in PIGL did not present thetypical CHIME syndrome phenotype." (PMID 29473937, 2018). "Although PIGL has been shown to be required for the transport of tetherin to the cell surface, viral infections are not a major symptom of PNH or CHIME syndrome patients." (PMID 24782851, 2014).
coloboma (4 papers, 2014 to 2024). An abnormality in which a part of a structure in one or both eyes is missing. "For example, biallelic variants in PIGL portrayed a syndromic association, including congenital heart disease, with coloboma, ichthyosiform dermatosis, mental retardation and ear anomalies (CHIME)." (PMID 39766333, 2024).
pulmonary arterial hypertension (2 papers, 2025). Pulmonary arterial hypertension (PAH) is a group of diseases characterized by mean pulmonary artery pressure >20 mmHg and elevated pulmonary arterial resistance leading to right heart failure. "Other genes in the signature, such as Chromosome 12 Open Reading Frame 42 (C12orf42) and phosphatidylinositol glycan anchor biosynthesis, class L (PIGL), have been associated with pulmonary arterial hypertension, smoking initiation, and FVC." (PMID 40894069, 2025).
melanoma (1 paper, 2023). A malignant, usually aggressive tumor composed of atypical, neoplastic melanocytes. "For instance, MEF2A, EMP2, ZNF440, PIGL, FRMD4B, and HIF3A are not only downregulated in TCGA-SKCM melanoma samples but also essential for restraining tumor growth in CRIPSR KO screens." (PMID 37904237, 2023).
personality disorder (1 paper, 2025). A diverse category of psychiatric disorders characterized by behavior that deviates markedly from the expectations of the individual's culture; this pattern of deviation is pervasive and inflexible and is stable over time. "For example, the region chr17p12-p11.2, significant in three of six analyses, contains PIGL, a gene associated with both lung function and personality disorders." (PMID 41295252, 2025). "Notably, the region 17:14860784-16319512 on chr17p12-p11.2, which includes the gene PIGL associated with both lung function and personality disorders, was found significant in three out of six analyses." (PMID 41295252, 2025).
genetic diseases (3 papers, 2018 to 2024). "Interestingly, human mutations affecting PIGL and PIGF, and up to 15 other GPI biosynthesis pathway genes have been related to human genetic disease with common clinical features such as congenital heart defects and neurodevelopmental disorders." (PMID 38819479, 2024).
PIGL also shares sentences with these, for which no sentence is quoted: Intellectual disability (3 papers); congenital heart disease (2); cancer (1); Cognitive impairment (1); glycosylphosphatidylinositol deficiency (1); hyperphosphatasia (1); Mabry syndrome (1); neurodevelopmental disorder (1); neurological disorder (1); preeclampsia (1); Progressive myoclonic epilepsy (1); tumor (1).